OR52B2 (olfactory receptor family 52 subfamily B member 2)
Description:
Odorant receptor.
Synonyms: OR11-70
Tractability: Small molecule: it belongs to a druggable protein family. Antibody: UniProt places it where antibodies can reach, with medium confidence; UniProt predicts a signal peptide or a membrane-spanning region; its Gene Ontology location is reachable by antibodies, with medium confidence.
Gene: Protein-coding gene on chromosome 11 (6,169,355 to 6,170,326, reverse strand). Ensembl gene ENSG00000255307.
Subcellular location: Cell membrane
Pathways (Reactome):
Sensory Perception: Expression and translocation of olfactory receptors
Gene Ontology:
Molecular function: olfactory receptor activity; G protein-coupled receptor activity
Biological process: detection of chemical stimulus involved in sensory perception of smell; G protein-coupled receptor signaling pathway; nervous system process
Cellular component: plasma membrane; membrane
Genetic constraint (gnomAD): Loss-of-function variants: 19 observed, 16.08 expected, observed/expected ratio (o/e) 1.18, 90% interval 0.82 to 1.71. The upper end of that interval is the gene's LOEUF score, 1.71, which puts it in group 6 of 6, group 1 being the genes least tolerant of losing a copy. Missense variants: 465 observed, 427.31 expected, observed/expected ratio (o/e) 1.09, 90% interval 1.01 to 1.17. Synonymous variants: 169 observed, 160.57 expected, observed/expected ratio (o/e) 1.05, 90% interval 0.93 to 1.2.
Homologues: Orthologues: dog OR52B2 (91% identical), macaque OR52B2 (88% identical), rat Or52b2 (88% identical), mouse Or52b2 (88% identical), pig OR52B2 (84% identical), tropical clawed frog or52d1 (54% identical), tropical clawed frog or52al1 (50% identical). Paralogues in human: OR52H1 (60% identical), OR52B6 (55% identical), OR52B4 (55% identical), OR52D1 (55% identical), OR52E8 (54% identical), OR52E4 (53% identical), OR52E2 (51% identical), OR52E6 (51% identical), OR52J3 (50% identical), OR52E5 (49% identical), OR52N2 (49% identical), OR52K1 (48% identical), and 39 more.
Diseases named in the same sentence as OR52B2 in open-access papers:
OR52B2 is named in the same sentence as 1 disease in open-access papers, as found by Europe PMC text mining. Sharing a sentence is not in itself a finding about the gene and the disease.
OR52B2 shares sentences with these, for which no sentence is quoted: cardiac disease (1 paper).